TSC2 (TSC complex subunit 2)
Diseases named in the same sentence as TSC2 in open-access papers (continued):
Sharing a sentence is not in itself a finding about the gene and the disease.
tumor (continued). "The WEE1 inhibitor MK1775 alone at a clinically relevant dosage (60 mg kg−1) already showed its inhibitory effect on Tsc2-null tumor growth in vivo." (PMID 30266942, 2018). "TSC1 and TSC2 respectively code for the hamartin and tuberin proteins, which act as tumor growth suppressors." (PMID 30236073, 2018). "Mutations in the tumour suppressor genes TSC1 and TSC2 are well-described activating mutations in the kinase domain of the mTOR pathway." (PMID 30220708, 2018). "However, eIF2αP may also control TSC2-deficient tumor formation via immune-regulatory pathways." (PMID 29449538, 2018). "In contrast, infusion of monocytes with increased mTORC1 activity following genetic ablation of TSC2 results in increased tumor growth and angiogenesis in host mice bearing tumor xenografts." (PMID 29104248, 2017). "Two independent tumor subclones were present at a CCF of ~50% each at day 0, with a BRCA2 V2620fs mutation, representing the surviving subclone, which also possessed a TSC2 P670S mutation, giving rise to subsequent samples." (PMID 29093439, 2017). "TSC2 is a GTPase-activating protein (GAP), which is rarely mutated in PDAC, and its mutation often causes a benign tumor." (PMID 28591720, 2017). "We here used a genetically engineered Tsc2+/- mouse model that spontaneously develops various types of renal lesions and confirmed the anti-tumour efficacy of GSK2126458 for tumours in an organ-appropriate environment." (PMID 28938574, 2017). "The experiments show that disrupting Tsc2 in mesenchymal cells does indeed mimic features of the human disease; the mice had shorter lifespans and they developed many tumours with dilated and winding blood vessels." (PMID 28695825, 2017). "Five of these CNA-bearing tumours also showed TSC1/TSC2 CN-LOH, and in all cases, a larger fraction of DNA was affected by the CN-LOH event than these CNAs, suggesting they occurred subsequently to a driving LOH event." (PMID 28643795, 2017). "It is suggested that tumor formation is initiated as a consequenceof at least two hits: asTSC1 and TSC2 are tumor suppressor genes, theinactivation of both TSC1 or both TSC2 alleles isnecessary for benign or malignant tumor formation." (PMID 28222202, 2017). "Genotyping revealed that the majority of the primary tumor variants were identified in MEN1 (42.2%), DAXX (11.1%), ATRX (10%), and TSC2 (7.8%) genes." (PMID 29212165, 2017). "IHC analysis revealed that tumor tissues derived from mice with injection of PDGFRα-overexpressing Tsc2−/− MEFs exhibited much stronger staining for Ki-67 than those in the control group." (PMID 28903387, 2017). "The most prevalent primary tumor variants were in the MEN1 (42%), DAXX (11%), ATRX (10%), and TSC2 (8%) genes." (PMID 29212165, 2017). "For example, mouse cells that lack Tsc2 produce more of a protein called galectin-3, which appears to help blood vessels and tumours to grow in cancers." (PMID 28695825, 2017). "The tumor suppressors Tsc1 and Tsc2 form the tuberous sclerosis complex (TSC), a regulator of mTOR activity." (PMID 29127155, 2017). "Next we explored the in vivo effect of combination administration of rapamycin and AG1295 by using a mouse tumor model with NTC/T2-null cells (a cell line with potent tumorigenicity derived from Tsc2−/− MEFs)." (PMID 28903387, 2017). "Mutations in TSC1 or TSC2 lead to the rare genetic condition, TSC, where patients develop cysts and tumours in multiple organs due to mTORC1 hyperactivity and uncontrolled cell growth." (PMID 28415776, 2017). "Altogether, our integrated analysis demonstrated that 13 of the 16 uRCC tumours with MTOR, TSC1, TSC2 or PTEN mutations exhibited hyperactive mTORC1 signals." (PMID 27713405, 2016).
tumor (continued). "Immunohistochemical analysis revealed that tumor tissues formed by injection of COX2-overexpressing Tsc2−/− MEFs exhibited much stronger staining for Ki-67 than those formed by the control cells." (PMID 27078846, 2016). "This is an autosomal dominant phacomatosis, due, in 60 % of cases, to spontaneous mutation in two tumor suppressor genes (TSC1 and TSC2)." (PMID 26861567, 2016). "TSC1 is known to stabilize TSC2 by forming a complex with TSC2 and the genetic data strongly implicate the complex between TSC1 and TSC2 as the functional unit for these tumour suppressors." (PMID 27387347, 2016). "For instance, transcription factors pleiotropically linked to stem cell migration (e.g. KITLG), telomere maintenance (e.g. POT1) and also tumor suppressors (e.g. TSC2)." (PMID 27264734, 2016). "It is also interesting to note that upregulation of certain proteins were somewhat counterintuitive, specifically TSC1, TSC2, and PDCD4 as these proteins are typically associated with tumor suppression." (PMID 25999352, 2015). "Gene product of TSC2 is believed to be a tumor suppressor and is able to stimulate specific GTPases." (PMID 26318033, 2015). "To determine if TSC-2 null tumour forming cells were able to attract wild type cells in an alternative system, we examined the presence of recruited wild type cells in an animal model of LAM lung pathology." (PMID 25978616, 2015). "GSK-3 inhibits mTORC1 signaling via phosphorylation of the tuberous sclerosis complex subunit 2 (TSC2) tumor suppressor." (PMID 26083118, 2015). "Speaking to this, it is possible that different tumor types that are prevalent in TSC patients, as well as those that define LAM disease, are derived from TSC1- or TSC2-deficient cells of different neural crest subtypes." (PMID 25505789, 2014). "Tumor suppressor function of TSC1/TSC2 is exerted by TSC2 that acts as GTPase Activating Protein (GAP) for small GTPase Rheb via its C-terminal domain." (PMID 25360538, 2014). "AMPK directly phosphorylates the tumour suppressing protein tuberous sclerosis complex (TSC2), inducing suppression of mTOR32." (PMID 24981420, 2014). "In tumor samples, loss of TSC1/TSC2 function resulted in subsequent loss of mTORC2 activity and mTORC1 hyperactivation." (PMID 25283550, 2014). "Hamartin (TSC1) and tuberin (TSC2), encoded by the tuberous sclerosis complex (TSC) genes, form a tumor-suppressor heterodimer which is implicated in PI3K-Akt signaling and acts as a functional inhibitor of the mammalian target of rapamycin (mTOR)." (PMID 24593867, 2014). "Inactivating TSC1 and TSC2 mutations cause tuberous sclerosis complex (TSC), an autosomal dominant disorder characterised by the occurrence of benign tumours in various organs and tissues, notably the brain, skin and kidneys." (PMID 24714658, 2014). "TSC2 protein forms a heterodimeric tumour suppressor complex with TSC1, which is at the crossroads of many different signalling pathways, and serves as a nexus for integrating extracellular growth factor signalling and nutritional availability." (PMID 24318044, 2014). "Results demonstrate that Rictor, TSC1, and TSC2 (all activators of mTORC2 signaling) have higher expression levels in ERα+ tumor samples compared to ER−." (PMID 25283550, 2014). "We present a model whereby the diverse, heterogeneous tumor burden in TSC patients is dependent on when first- and second-hit mutations in TSC1 or TSC2 occur during development and into adulthood." (PMID 25505789, 2014). "In a large-scale small interfering RNA (siRNA) screen, we found that knockdown of the tumor suppressors Folliculin (Flcn) and Tsc2 prevent ESC commitment." (PMID 23582324, 2013).
tumor (continued). "TSC, characterized by benign hamartomas in multiple organs, is caused by mutations in either of the two tumor suppressor genes encoding hamartin (TSC1) and tuberin (TSC2)." (PMID 23514105, 2013). "The human homologue of TSC2 is an important tumor suppressor, and our study provides new insight into how its regulation controls regenerative processes." (PMID 23144631, 2012). "TSC and LAM are caused by mutations of one of two tumor suppressor genes, TSC1 and TSC2, located on chromosome 9q34 or chromosome 16p13, respectively." (PMID 22719903, 2012). "To test this idea, we used the FDA-approved drug imatinib (gleevec) to treat mouse tumors formed by implanted tsc2ang1 cells, isolated from a cutaneous sarcoma that arose in a tsc2 heterozygous mouse and a well-validated model of TS-related neoplasia." (PMID 22765013, 2012). "TSC1 or TSC2 mutations can cause TSC, a syndromic disorder characterized by tumor growth in multiple organs, including the brain." (PMID 22558107, 2012). "Considered together, the Tsc2- tumor cells exhibit metabolic plasticity beyond their dependence on glycolysis." (PMID 22018000, 2011). "Our Tsc2-null tumor xenograft model utilizes tumorigenic LEF2 cells derived from an Eker rat renal tumor." (PMID 22018000, 2011). "Mutations in several tumour-suppressor genes (such as TSC1, TSC2, LKB1, PTEN, VHL, NF1, and PKD1) trigger the development of different diseases." (PMID 21904669, 2011). "TSC1 is an established tumor suppressor gene in UC that exert most of its regulatory function in a complex with TSC2." (PMID 21533174, 2011). "When applied to an in vivo model of Tsc2-null tumor, 2-DG suppressed tumor growth by reducing cell proliferation whereas a diet free of carbohydrate resulted in larger tumors with increased zones of liquefaction." (PMID 22018000, 2011). "We used a subcutaneous Tsc2-/- tumor model to evaluate the efficacy of two VEGF inhibitors (sunitinib and bevacizumab), asparaginase, and a microtubule inhibitor (vincristine)." (PMID 20146790, 2010). "In this study, we evaluated three novel drug classes in our Tsc2-/- subcutaneous tumor model: an enzyme that interferes with amino acid metabolism (asparaginase), two VEGF inhibitors (sunitinib and bevacizumab), and a microtubule inhibitor (vincristine)." (PMID 20146790, 2010). "We have previously shown that single agent IFN-γ, combination IFN-γ plus mTOR inhibitor, and combination sorafenib plus mTOR inhibitor are effective in the Tsc2-/- subcutaneous tumor model." (PMID 20146790, 2010). "CP1's ability to interact with and protect TSC2 from inactivating phosphorylation by AKT retained TSC2 at the membrane, where it was active and able to exert its tumor suppressor function to repress mTOR." (PMID 20169078, 2010). "The Tsc2-/- subcutaneous tumor model is a good generic model for TSC-related tumors because loss of heterozygosity (LOH) has been found in many TSC-related kidney and brain tumors." (PMID 20146790, 2010). "While the role of AMPK in DR has not been tested yet, the histone deacetylases Rpd3 and Sir2, and the tumor suppressors Dmp53 and Tsc2, a member of the TOR pathway, have all been shown to be necessary for lifespan extension in different methods of DR in flies." (PMID 19239417, 2009). "We observed a dramatic 94.5% reduction in tumor burden in Tsc2+/- mice treated with one month of daily rapamycin treatment before and after five months of weekly rapamycin therapy." (PMID 19368729, 2009). "We also evaluated the utility of a VEGF pathway inhibitor (sorafenib), a HMG-CoA reductase inhibitor (atorvastatin), and an MMP inhibitor (doxycycline) using the subcutaneous Tsc2-/- tumor model." (PMID 19368729, 2009). "In most tumor cell lines, including Tsc1 null and Tsc2 null MEF cell lines, treatment with rapamycin or RAD001 leads to phosphorylation of AKT at the S473 site, and increased activation." (PMID 19527517, 2009).
tumor (continued). "We also used a Tsc2-/- subcutaneous tumor model to evaluate other classes of drugs including sorafenib, atorvastatin, and doxycycline." (PMID 19368729, 2009). "Allelic loss and intragenic mutation have been demonstrated in tumours in the Eker rat and transgenic expression of TSC2 in the Eker rat and Eker tumour cell lines support its tumour-suppressor function." (PMID 19506736, 2008). "Western blot analysis was performed to examine differences in TSC2 protein expression between CT-2A cells and syngeneic mouse astrocytes as well as between tumor tissue and contra-lateral normal brain tissue from tumor-bearing mice." (PMID 18474106, 2008). "Although there is considerable inter-strain variability in tumour development this appears to be more rapid in TSC2 than TSC1 heterozygotes." (PMID 19506736, 2008). "In order to confirm the results in patient tumor samples, the methylation status of the TSC2 gene promoter was examined by COBRA." (PMID 18538015, 2008). "Loss of heterozygosity was studied using matched blood and tumor DNA samples and microsatellite markers from the TSC1, TSC2 and PTEN candidate regions." (PMID 18538015, 2008). "mTOR inhibitors have anti-neoplastic potential since mutations in LKB1, TSC2, or PTEN tumor suppressor genes produce aberrant mTOR activation in certain neoplastic conditions." (PMID 18474106, 2008). "The only aspects of the model that were modified during the simulations were activity-levels reflecting the immediate effects of either the underlying tumor mutations (Ras and PTEN) or the perturbations (mTOR-Raptor and TSC2 targeted manipulation)." (PMID 18463702, 2008). "Rapamycin has been shown to induce apoptosis, decrease proliferation, and reduce tumor size in the Eker rat model and in TSC2+/− mice." (PMID 18958173, 2008). "For many years, the prevailing model has been that the hamartomas of TSC develop through a two-hit mechanism in which there is complete loss of expression of functional TSC1 or TSC2, supported by findings of loss of heterozygosity (LOH) in TSC tumour samples." (PMID 19506736, 2008). "We have previously compared the combination of CCI-779 plus IFN-γ with single agent CCI-779 and single agent IFN-γ in nude mice bearing Tsc2-/- tumors and found a significant reduction in tumor growth and improved survival with combination therapy." (PMID 17986349, 2007). "To determine the exact contribution of TSC2, we tested tumor cells transfected with control and TSC2 siRNAs." (PMID 17597835, 2007). "We have also directly compared the efficacy of rapamycin with that of CCI-779 in a Tsc2-/- tumor-bearing mouse model." (PMID 17986349, 2007). "Here, we report that rosiglitazone increased the phosphorylation of TSC2 highlighting the relevance of this tumor suppressor in mediating the effects of rosiglitazone." (PMID 17597835, 2007). "The tumor suppressor genes TSC1 and TSC2 encode the proteins hamartin and tuberin, respectively." (PMID 39936727, 2025). "Genetic testing indicated multiple tumor-specific mutations including whole-chromosome losses (3, 6, 10, 11, 13, 14, 17, 18, 21, and X) and point mutations inTP53,NF1, andPTEN.Germline mutation testing was within normal limits, including normalTSC1/TSC2." (PMID 40018440, 2025). "Notably, HPV-16 E6 proteins can bind and degrade TSC2, further activating mTORC1 and enhancing tumor cell proliferation, metastasis, and resistance to apoptosis by inhibiting pro-apoptotic proteins such as Bad and Bax." (PMID 40486961, 2025). "Furthermore, IL-6 was recently shown to be overexpressed in TSC2 disease models, and inhibition with IL-6 antagonists was shown to reduce tumour growth." (PMID 41013689, 2025).
tumor (continued). "Recent studies demonstrate that lung-targeted lipid nanoparticles delivering functional TSC2 mRNA can restore tumor suppressor activity, inhibit mTORC1 signaling, and reduce cystic lung damage in preclinical models, offering a potential disease-modifying approach." (PMID 41180734, 2025). "TSC2, a critical regulator of the mTORC1 pathway, acts as a tumor suppressor." (PMID 40486961, 2025). "We performed scRNAseq on control and Tsc2-knockout uteri to gain insight into the changes that may have developed in the immune cells and structural cells, both of which influence the tumor microenvironment." (PMID 40893807, 2025). "To generate EV, mimicking EV released from metastasizing/circulating LAM cells (metastasis EV), we isolated EV from 621 – 101 or TSC2 addback, floating in culture media, spheres grown for 7 days in ultra-low attachment plates, as they mimic micrometastases or circulating tumor cell spheroids." (PMID 40166013, 2025). "Thus, CHUK, IKBKB gene products, and co-chaperones FKBP5 (FKBP51), TSC1, and TSC2 interact with Hsp90 and behave like tumor suppressors, while AKT1 shows oncogenic behavior and is involved in the enhanced activity of many signaling pathways." (PMID 39337357, 2024). "Furthermore, estrogen significantly impacts the multiplication of LAM tumor cells, and it also expedites the spread of TSC2 mutant tumor cells and stimulates LAM cell expansion." (PMID 38877584, 2024). "Furthermore, IL-6 was recently shown to be over-expressed in TSC2-disease models, and inhibition with IL-6 antibody antagonists was shown to reduce tumour growth." (PMID 39070657, 2024). "The TSC1 and TSC2 genes are classified as tumor suppressor genes and function according to Knudson’s two-hit hypothesis, which means that both alleles must be damaged for tumor formation." (PMID 37232723, 2023). "Interestingly, while all 3 CAR-T cell groups initially suppressed tumor growth, the TSC2–/– were the least effective in controlling tumor growth over time." (PMID 37788104, 2023). "Research has found that some tumor tissues have lower TSC2 expression levels than normal tissues." (PMID 37251941, 2023). "We also confirm that the mTOR pathway is strongly implicated in the pathogenesis of this tumor mainly through MTOR, TCS1, and TSC2 mutations, but other genes could also be involved in the pathway activation, especially in LOTs without “canonical” mutations." (PMID 37845471, 2023). "Having found that B7-H3 knockdown does not affect Tsc2-deficient tumor growth in immunodeficient mice, we next sought to define the infiltrating immune cells that are regulated by B7-H3 using Cytometry by time-of-flight (CyTOF)." (PMID 36869048, 2023). "This could reflect metabolic changes and/or synthetic changes coupled to mTORC1 activation that enabled TSC2 SA T cells to better survive and proliferate within the hostile tumor microenvironment." (PMID 37788104, 2023). "Although frame-shift mutations in TSC2 are common in multiple disease states, the pathologic TSC2-p.K1165fs frame-shift mutation involving exon 30 seen in this tumor has not been previously reported in literature." (PMID 37041531, 2023). "Due to the characteristic symptoms and specific mutations of the TSC1 or TSC2 genes, TSC-RAML is quite different from S-AML in many aspects, including multifocal, a larger tumor volume and a higher incidence of tumor rupture, which is the main cause of death among adult TSC-RAML patients." (PMID 36891236, 2023). "Loss-of-function TSC1 or TSC2 mutations constitutively switch Rheb to an active GTP-bound state that then aberrantly activates mTORC1, leading to metabolic transformation and uncontrolled tumor growth and encouraging angiogenesis in hypoxic tissues." (PMID 36551683, 2022). "FLCN and Tsc2 are additions to the growing list of tumor suppressors that interact with Hsp90." (PMID 35883484, 2022).